CST6 (cystatin E/M)
Diseases named in the same sentence as CST6 in open-access papers (continued):
Sharing a sentence is not in itself a finding about the gene and the disease.
tumor (continued). "Moreover we have recently shown that CST6 is epigenetically silenced in Circulating Tumor Cells (CTC) isolated from peripheral blood of operable and metastatic breast cancer patients." (PMID 23088560, 2012). "Importantly, xenograft metastasis analyses by intracardiac injection of these cancer cells into mice showed that CST6 significantly reduced the number of TRAP+ osteoclasts along the tumor-bone interface and inhibited bone matrix destruction, leading to suppression of bone metastasis." (PMID 34815788, 2021). "To further investigate the types of cells expressing CTHRC1, CST6, and AKR1B1 in tumor tissues, we utilized the GEO database datasets EMTAB8107 and GSE167297 to conduct a detailed analysis of CTHRC1, CST6, and AKR1B1 expression in STAD." (PMID 40978044, 2025). "Our study found that CST6 acts as a tumor-promoting molecule in NPC, promoting lymphatic endothelial cell tube formation and migration and that high expression of CST6 affects the prognosis of patients with NPC." (PMID 40745648, 2025). "With statistically significant differences, CTHRC1, CST6, and AKR1B1 were highly expressed in the tumor and lowly expressed in the normal in both paired and unpaired samples of patients with GC (p < 0.05)." (PMID 40978044, 2025). "CST6 has a high binding affinity for Legumain (LGMN), a lysosomal cysteine protease involved in antigen processing, neuronal cell death, and tumour cell invasion." (PMID 40234537, 2025). "CKS1B+ neoplasm, C16orf89+ neoplasm, CST6+ neoplasm, H2AC6+ neoplasm and MTND2P13+ neoplasm all demonstrate heightened tumour stemness." (PMID 38946232, 2024). "The co‐expression of any 1 gene from Group A (C19orf33, S100A14, and RHOD; count ≥1) and any 1 gene from Group B (CST6, CD44, TM4SF1, and TACSTD2; count ≥1) in a single tumor cell was defined as a MIC." (PMID 38864342, 2024). "CKS1B+ neoplasm, CST6+ neoplasm and MTND2P13+ neoplasm are more prevalent in advanced LUAD, while DLX5+ neoplasm is more common in early‐stage LUAD." (PMID 38946232, 2024). "As the EMT score was significantly influenced by tumor purity, we estimated the relationship between EMT and CST6 using partial correlation to remove the confounder." (PMID 34603393, 2021). "The balance between these two critical cell growth regulators in RMS has a profound impact on tumor cell growth and apoptosis through co-regulation of essential cell growth and cell cycle control genes such as CDKN1A (p21), PTEN, NDRG1 and CST6." (PMID 29719592, 2018). "We then expanded this analysis to additional targets including cystatin 6 (CST6), a cysteine protease inhibitor which functions as a tumor suppressor and has been identified as a repression target of TBX2 through a mechanism involving EGR1." (PMID 29719592, 2018). "Re-expression of BNC1, CST6, and SFRP1 suppressed the growth of RCC cell lines, whereas RNAi knock-down of BNC1, SFRP1, and COL14A1 increased their growth, suggesting tumor suppressor activity." (PMID 28326264, 2015). "Together these data suggest that the mechanism through which CST6 induces apoptosis is due to its inhibition of LGMN activity and that TBX2 drives tumor growth through maintenance of LGMN activity." (PMID 24742492, 2014). "In conclusion, the present study showed aberrant tumor-specific methylation alterations for APC, BIN1, BMP6, BRCA1, CST6, ESR-b, GSTP1, P14, P16, P21, PTEN and TIMP3 in the studied cohort." (PMID 22695536, 2012). "Hierarchical clustering showed significant hypermethylation patterns for serum and tumor tissue compared with normal tissue for seven genes (APC, BIN1, BMP6, BRCA1, CST6, P16 and TIMP3)." (PMID 21283676, 2011). "Two-way hierarchical clustering in serum and tumor tissue showed significant hypermethylation patterns of seven genes (APC, BIN1, BMP6, BRCA1, CST6, P16 and TIMP3) compared with normal tissue." (PMID 21283676, 2011).
tumor (continued). "The association between the quantity of CST6 methylation and the expression statuses of cystatin M, ER, PR, and HER4 in tumor tissues was analyzed." (PMID 21092257, 2010). "In a study recently published, basal-like tumour cell lines were characterized by the concomitant hypermethylation of a six gene panel (CDH1, CEACAM6, CST6, ESR1, LCN2, SCNN1A)." (PMID 20338046, 2010). "We further investigate the types of cells expressing CTHRC1, CST6, and AKR1B1 in tumor tissues, and the results indicate that CTHRC1, CST6, and AKR1B1 expression exhibits significant variability in GC, especially within key immune cell populations such as CD8 T cells, B cells, and DCs." (PMID 40978044, 2025). "To validate our computational findings, we performed experimental validation using qRT-PCR, confirming significant overexpression of CTHRC1, CST6, and AKR1B1 in GC tissues compared to adjacent normal tissues (p < 0.05), with HPA data further confirming elevated protein levels in tumor tissues." (PMID 40978044, 2025). "Moreover, our data suggest a potential crucial role for CTHRC1, CST6, and AKR1B1 in the mitochondria process of tumor cells." (PMID 40978044, 2025). "Hypermethylation was found in 8/18 and 10/18 tumor samples for LAD1 and CST6, respectively." (PMID 39051186, 2024). "CST6, TRIM29, and CSTA (an ER target gene) possessed tumor-suppressive actions toward BC." (PMID 37370814, 2023). "We next performed single-cell RNA-Seq (scRNA-Seq) on BM mononuclear cells from tumor-bearing mice treated with and without CST6." (PMID 35881476, 2022). "Since CST6 blocks RANKL signaling, which is a key pathway for osteoclastogenesis, it may well contribute to the dormancy of tumor cells." (PMID 35881476, 2022). "Epigenetic alterations, like DNA methylation, in the promoter regions of tumor/metastasis suppressor genes, such as SOX17, BRMS1, and CST6 in EpCAM+ CTCs isolated from individuals with BC, are known to be correlated with enhanced tumor metastasis and poor prognosis." (PMID 35303879, 2022). "The proportion of BM B cells was dramatically decreased in tumor-bearing mice with or without CST6 treatment, while macrophages were notably decreased in MM mice treated with CST6 protein." (PMID 35881476, 2022). "CST6 was also shown overexpressed in triple-negative breast cancer and oral cancer, facilitating the tumor metastatic process." (PMID 34603393, 2021). "Both BMP4 and CST6 are metastasis suppression genes downregulated in 231_HM.LNm5 tumour cells relative to non-metastatic 231_ATCC tumour cells, and both contain CpG islands spanning their transcription start sites in their 5′ proximal regions." (PMID 29720474, 2018). "The quantitative DNA methylation analysis of the candidate genes showed higher methylation proportion in the primary tumor tissue than that of the matched normal tissue and the differences were significant for the APC, BIN1, BMP6, BRCA1, CST6, ESR-b, P16, PTEN and TIMP3 promoter regions (P<0.05)." (PMID 22695536, 2012). "However, despite data suggesting that cystatin E/M has tumor suppressive capabilities, we did not detect lower levels in the metastatic versus the primary cell lines." (PMID 20074384, 2010). "Notably, CST6 protein did not directly affect the growth of tumor cells." (PMID 34815788, 2021). "A correlation study of the methylation proportion of DNA in serum versus cancerous and normal breast tissue revealed a correlation between tumor tissue and serum for BMP6, BRCA1, CST6, GSTP1, P16 and TIMP3 genes but not with the matched normal tissue." (PMID 21283676, 2011). "Alternatively, a clear association between the epithelial cell adhesion molecule (EpCAM)-positive CTC-fraction and circulating tumor DNA (ctDNA) for promotor methylation of the transcriptional regulator SOX17, but not for CST6, was found for both patients with early and metastatic breast cancer." (PMID 33919854, 2021).
cancer (24 papers, 2008 to 2025). A tumor composed of atypical neoplastic, often pleomorphic cells that invade other tissues. "CST6 expression has been previously associated with its epigenetic regulation by methylation of the promoter region in several cancer types." (PMID 34603393, 2021). "It has been reported that CST6 down-regulation was observed in metastatic primary cancer cells and loss of its function has a vital role in the progression of various types of cancers including breast cancer, glioma, and lung cancer." (PMID 34715860, 2021). "Aberrant TBX2 expression is likely to be just one of many pathways leading to loss of CST6 in cancers." (PMID 24742492, 2014). "More recently, loss of CST6 expression has been reported in a number of other cancer types including cervical, glioma, prostate and gastric cancers." (PMID 24742492, 2014). "Furthermore, by differential gene expression analysis on total cancer cells in the 2 cultures, we identified several dormancy-associated genes such as Cst6, Mgp, Mme, Gas6, etc. to be up-regulated in the TSO culture compared to monotypic culture." (PMID 37699010, 2023). "Suppression of BMP4 and CST6 levels in 231_HM.LNm5 cells relative to 231_ATCC cells was retained in 2D culture, suggesting that the mechanism(s) underlying downregulation are cancer cell intrinsic." (PMID 29720474, 2018). "CST6 is a cysteine protease inhibitor that demonstrates complex and context-dependent functions in cancer pathogenesis." (PMID 40978044, 2025). "Several peptides mimicking the function of CST6 are able to suppress cancer cell-induced osteoclastogenesis and bone metastasis." (PMID 37240298, 2023). "The functional role of CST6, as well as its relatively small size and the secretory nature, argues for the clinical potential of this protein in cancer treatment." (PMID 34815788, 2021). "It was found that CST6 knockdown in cancer cells enhanced CM-induced p38 phosphorylation and osteoclast maturation of RAW264.7, while SB203580 treatment showed the opposite effect." (PMID 34815788, 2021). "The expression level of CST6 and epithelial cell infiltrate score were varied in cancer types, while the positive correlation between the two variables was observed in most cancers." (PMID 34603393, 2021). "In summary, this first CST6 pan-cancer study improves the understanding of the dual functional effects on CST6 in different types of human cancer." (PMID 34603393, 2021). "Collectively, CST6 played crucial and disparate roles in the pathogenesis and development of cancer." (PMID 34603393, 2021). "Due to the limited normal sample size for several cancer types, we included the normal tissue of the GTEx datasets and evaluated the expression difference of CST6." (PMID 34603393, 2021). "To verify the expression pattern of CST6 across cancer types, we collected the MMDs of more than 7,000 samples from 11 cancers with a standard process." (PMID 34603393, 2021). "Previous studies of CST6 expression in cancer were limited to sample sizes and focused on a single cancer type." (PMID 34603393, 2021). "Consistent with the known dual role of CST6, we found that there was a broad spectrum of CST6 expression across cancer types." (PMID 34603393, 2021). "The expression of CST6 was positively related to most epithelial cells, while the negative correlation between CST6 and plasma cell was observed in most cancer types." (PMID 34603393, 2021). "In the present study, we explored the expression pattern of CST6 in multiple cancer types across ∼10,000 samples from TCGA (The Cancer Genome Atlas) and ∼8,000 samples from MMDs (Merged Microarray-acquired Datasets)." (PMID 34603393, 2021). "In this study, we performed a systematic evaluation of the expression pattern of CST6 across cancer types from TCGA and MMDs." (PMID 34603393, 2021). "Cancer cell-derived CST6 enters osteoclasts by endocytosis and suppresses the cysteine protease CTSB, leading to up-regulation of the CTSB hydrolytic substrate SPHK1." (PMID 34815788, 2021).
cancer (continued). "We found that the dynamic expression alteration of CST6 was consistent with dual function in different types of cancer." (PMID 34603393, 2021). "Our first pan-cancer study for CST6 provided novel insights into its dual function in the development of cancer." (PMID 34603393, 2021). "We further identified several peptides mimicking the function of CST6 to suppress cancer cell-induced osteoclastogenesis and bone metastasis." (PMID 34815788, 2021). "Based on all these studies, we strongly believe that the reliable and easy detection of CST6 methylation in clinical samples will be of great importance for cancer research." (PMID 23088560, 2012). "When CST6 isn't functioning properly, it can lead to changes in the proteolysis of tissue structures, which could potentially speed up the spread of cancer cells." (PMID 39416432, 2024). "Furthermore, in the high-risk group, AFP, CST6, CGB5, and ELANE were significantly expressed, indicating their potential roles as cancer-promoting genes in the development of STAD." (PMID 37377916, 2023). "Indeed, previous studies have solidly demonstrated that CST6 suppresses the proliferation, survival 12, 30, 31 and metastasis of cancer cells." (PMID 34815788, 2021). "The dysfunction of CST6 contributed to the alterations in proteolysis of tissue architecture, which might accelerate the spread of cancer cells." (PMID 34603393, 2021). "Furthermore, treating pre-osteoclasts with CM from CST6-overexpressing cancer cells also diminished RANKL-induced p38 phosphorylation in pre-osteoclasts." (PMID 34815788, 2021). "Increasing evidence has demonstrated the dual functional effects of CST6 in cancer progress." (PMID 34603393, 2021). "Similarly, most of the genes specifically expressed in normal epithelial cells were the pancreatic epithelial cell functional genes, and the primary cancer cells expressed the genes that were highly associated with the development of PDAC, including TFFs, S100A2, PSCA, CST6 and many others." (PMID 36307773, 2022). "However, the relationship between the expression and the DNA methylation of CST6 in pan-cancer level remains unclear." (PMID 34603393, 2021). "Finally, the clinical association analysis further revealed the dual function of CST6 in cancer, and a combination of the epithelial cell infiltration and CST6 expression could predict the prognosis for SKCM patients." (PMID 34603393, 2021). "Next, we observed a significant negative correlation of CST6 methylation and its expression in more than half (21 out of 32, Pearson correlation < 0 and p-value < 0.05) of the cancer types." (PMID 34603393, 2021). "None of the 7 (0%) histologically cancer-free specimens from reduction mammoplasty was found to be methylated for CST6 promoter." (PMID 23088560, 2012). "However, a comprehensive research about the expression pattern and functional effects of CST6 in pan-cancer level is still lacking." (PMID 34603393, 2021). "PITX1, CST6 and HOPX were reported their downregulation in various types of human cancer, and PRSS27 was known to be highly expressed in nonkeratinizing stratified squamous epithelia of human esophagus and its dysregulation was supposed to be related to characteristics of carcinoma." (PMID 29137437, 2017). "However, a comprehensive and systematic analysis for CST6 in pan-cancer level is still lacking." (PMID 34603393, 2021).
kidney disease (1 paper, 2025). "Despite the link between CST6 and protease functioning, the exact mechanism that affects kidney disease has not been described." (PMID 40004202, 2025).
CST6 also shares sentences with these, for which no sentence is quoted: invasive breast carcinoma (3 papers); breast (2); liver cancer (2); renal carcinoma (2); acute myocardial infarction (1); atopic dermatitis (1); benign breast tumors (1); benign tumor (1); diffuse large B-cell lymphoma (1); ductal adenocarcinomas (1); ductal carcinoma in situ (1); Harlequin ichthyosis (1); hypotrichosis (1); ichthyosis (1); infection (1); intestinal polyp (1); keloid (1); kidney tumor (1); leukemia (1); lung adenocarcinoma (1); malignant glioma (1); melanoma in situ (1); metastatic cancers (1); ocular melanoma (1); oral cancer (1); ovarian carcinoma (1); pancreatic adenocarcinoma (1); pancreatitis (1); pleural tumors (1); polyp (1).
A further 11 diseases each share a sentence with CST6 in 1 paper.